FEN1 (flap structure-specific endonuclease 1)
Diseases named in the same sentence as FEN1 in open-access papers (continued):
Sharing a sentence is not in itself a finding about the gene and the disease.
glioma (7 papers, 2017 to 2023). A benign or malignant brain and spinal cord tumor that arises from glial cells (astrocytes, oligodendrocytes, ependymal cells). "As DNA-PKcs-deficient glioma cells are addicted to FEN1 mediation to overcome DNA replication stress, FEN1 holds significant promise as a therapeutic agent for DNA-PKcs-deficient cancers." (PMID 35414100, 2022). "In our panel of two glioma cell lines, M059K and U251 cells, we observed that FEN1 deficiency significantly and consistently reversed resistance to TMZ, cisplatin and MMS, as indicated by cell viability and survival analyses." (PMID 35414100, 2022). "Our study confirms the essential role of DNA replication regulation in glioma and highlights that DNA-PKcs-deficient glioma cells are particularly addicted to complementary FEN1-mediated repair signaling." (PMID 35414100, 2022). "Collectively, these findings consistently support a scenario in which deficiency of FEN1 and DNA-PKcs causes cell growth inhibition and aggressive decline in the migration and invasion of glioma and other tumor cells." (PMID 35414100, 2022). "The elevated expression of the human protein FEN1 in DNA-PKcs-deficient glioma tumors affects various cellular processes and has been largely reported to be associated with cell cycle and cancer progression." (PMID 35414100, 2022). "DNA-PKcs deficient glioma cells are highly dependent on FEN1/BRCA1/RAD51 to survival and counteract replication stress." (PMID 35414100, 2022). "The coupling of FEN1 and DNA-PKcs deficiency resulted in dramatic replication fork collapse, genome instability and synthetic lethality in glioma cells, highlighting a promising strategy for glioma therapy, particularly for glioma cells harboring oncogene mutations." (PMID 35414100, 2022). "FEN1 polymorphisms and variant genotypes are associated with glioma susceptibility." (PMID 29033691, 2017). "Strong invasion and migration are distinctive characteristics of glioma cells; therefore, we next investigated the influence of FEN1 and DNA-PKcs inhibition on the invasion and migration ability." (PMID 35414100, 2022). "Correlation analysis of 173 glioma patient samples (r = 0.52, p < 0.001) showed that FEN1 was positively correlated with WRN expression." (PMID 35414100, 2022). "To determine the role of the FEN1-WRN complex in the DNA replication progression of glioma cells, we next measured the fraction of stalled and active replication forks in M059K cells transfected with siFEN1, siWRN and the combination of siFEN1 and siWRN." (PMID 35414100, 2022). "To investigate the effect of high FEN1 level in glioma progression and clinical prognosis, we divided glioma samples into FEN1 high and low expression groups then investigated the FEN1-related mutational landscape." (PMID 35414100, 2022). "Collectively, these in vivo experiments confirmed the synthetic lethality between FEN1 and DNA-PKcs in glioma cells." (PMID 35414100, 2022). "Inhibition of FEN1 induces homologous recombination deficiency through impaired expression and assembly of BRCA1 and RAD51 in multiple glioma cell types and sensitizes these cells to the effects of DNA-PKcs deficiency." (PMID 35414100, 2022). "Therapeutically, genetic depletion or molecular inhibition of FEN1 and DNA-PKcs perturb glioma progression." (PMID 35414100, 2022). "GO analysis indicated significant enrichment for multiple pathways of FEN1 associated with cellular progression including DNA replication and MCM complex in glioma samples." (PMID 35414100, 2022). "In our previous studies, we reported the synthetic lethal interaction of miR-1193 and DNA-PKcs in glioma and the potential regulation of FEN1 signaling in mediating glioma cells survival." (PMID 35414100, 2022). "In summary, our findings provide the first evidence that FEN1 has significantly increased expression in glioma cells, tissues, and patient samples and function as an addictive dependent flat regulator for glioma cells survival." (PMID 35414100, 2022).
glioma (continued). "FEN1 depletion is a promising approach to glioma therapy by reducing HR-mediated DSB repair capacity." (PMID 35414100, 2022). "Triggered stalled fork frequency and a further decrease in fork progression was observed in multiple glioma cells with both FEN1 and DNA-PKcs dysfunction after specific inhibitor treatment." (PMID 35414100, 2022). "Downregulation of FEN1 in glioma cells significantly increases its sensitivity to methylation drugs, such as methyl methanesulfonate and temozolomide." (PMID 33827468, 2021). "It affects the occurrence and development of glioma by regulating a series of tumor-related genes, such as FEN1, CCL3, PLCB1, NRAS and PIK3s, and activation of apoptosis signaling pathways." (PMID 29033691, 2017). "Overall, this study indicated that PHF20 is a pivotal upstream gene that influences the occurrence and development of glioma by regulating a series of tumor-related genes, like FEN1, CCL3, PLCB1, NRAS and PIK3s, and involved in apoptosis signaling pathways." (PMID 29033691, 2017). "A similar influence of sc-13 combined with another DNA-PKcs inhibitor, vx-984, was observed in multiple glioma cells, but the extent of the effects was different in other cancer cell lines, such as A549 and Huh-7 cells, reflecting promising targeting of FEN1/DNA-PKcs in tumor therapy." (PMID 35414100, 2022). "Further research on FEN1/DNA-PKcs may provide novel insights into glioma diagnosis and treatment, as well as significantly advance therapies in clinical personalized treatment." (PMID 35414100, 2022). "We next assessed whether combination treatment with FEN1 and the DNA-PKcs inhibitors sc-13 and NU-7441 can inhibit glioma tumor establishment in vivo." (PMID 35414100, 2022). "To confirm this conclusion, we also analyzed fork degradation upon effective FEN1 and DNA-PKcs depletion by treating two additional glioma cell lines, U251 and U87MG cells, with the FEN1 inhibitor sc-13 and the DNA-PKcs inhibitor NU-7441, which can be used both in vitro and in vivo." (PMID 35414100, 2022). "Upregulation of FEN1 expression was also found to be related to poor survival for glioma patients." (PMID 35414100, 2022). "To investigate the role of FEN1 in glioma cells proliferation, we performed proximity ligation assays (PLAs) using specific antibodies against FEN1 and the heterotrimeric replication protein A (RPA) complex, which stabilizes ssDNA intermediates formed during DNA replication." (PMID 35414100, 2022). "Therefore, we next examined the synergy between FEN1 and DNA-PKcs in response to replication stress and investigated the further functional interplay between FEN1 and DNA-PKcs on glioma cell growth." (PMID 35414100, 2022). "Moreover, as FEN1 regulates the expression and function of many molecules, there may be additional effects of FEN1 inhibition that contribute to sensitization of glioma cells to DNA-PKcs dysfunction, either cooperating with BRCA1/2, RAD51 or WRN." (PMID 35414100, 2022). "Regarding the function of FEN1 in glioma progression, we hypothesized that a therapeutic effect can be optimized by targeting DNA replication via FEN1 inhibition and combining the effects of FEN1-mediated DNA damage signaling and clinical reagents that drive survival-related stress." (PMID 35414100, 2022). "That is, upregulated FEN1 expression results in prolonged genome stability and constitutive activation of DNA replication in TMZ resistant glioma cells." (PMID 35414100, 2022). "To understand the expression of FEN1 in glioma cells, we used The Cancer Genome Atlas (TCGA) datasets to obtain and compare genomic data of patients with glioma and non-cancer patients." (PMID 35414100, 2022). "We labeled FEN1, BRCA1 and RAD51 in glioma mouse samples and observed decreased BRCA1 and RAD51 expression upon treatment with the specific FEN1 inhibitor sc13, confirming the regulatory role of FEN1 on BRCA1 and RAD51 in glioma cells." (PMID 35414100, 2022).
glioma (continued). "FEN1 expression was significantly overexpressed in glioma patients compared to that in non-cancer patients." (PMID 35414100, 2022). "Therefore, FEN1 is a key regulator of BRCA1 and RAD51 protein levels and function in glioma cells." (PMID 35414100, 2022).
neuroblastoma (7 papers, 2017 to 2025). Neuroblastoma (NB) is the most common solid, extracranial childhood tumor. "The high expression of DNA ligase 3, PARP1, and FEN1 is significantly associated with poor overall survival in neuroblastoma." (PMID 41189817, 2025). "Overexpression of FEN1 is correlated with poor overall survival, high risk, and advanced stage in neuroblastoma." (PMID 41189817, 2025). "A study on Chinese children observed a strong correlation between genetic variants of the FEN1 gene and neuroblastoma risk Genomic alterations in DNA damage response–related genes are frequently observed in high-risk NBL." (PMID 34745201, 2021). "Downregulation of repair proteins FEN1 and CBX8 may cause impaired DSB repair that leads to enhanced DSB accumulation, increasing apoptosis in stage 4S neuroblastoma." (PMID 41189817, 2025). "The expression of FEN1, PARP1, and DNA ligase 3 significantly increases in high-risk neuroblastoma." (PMID 41189817, 2025). "The downregulation of FEN1 involving MMEJ may also help protect stage 4S neuroblastoma tumors from chromosomal rearrangements resulting from the error-prone repair mechanism." (PMID 41189817, 2025).
Autoimmunity (6 papers, 2013 to 2025). The occurrence of an immune reaction against the organism's own cells or tissues. "The mutations in Flap endonuclease 1 (Fen1), which is one of key components in long-patch DNA base-excision repair, resulted in autoimmunity, chronic inflammation and various cancers." (PMID 33585082, 2021). "A nuclease-deficient Fen1 mutant mouse model displayed a marked predisposition to chronic inflammation and autoimmunity." (PMID 32547565, 2020). "Mice carrying with FEN1 E160D mutation were predisposed to autoimmunity, chronic inflammation, and cancers, which results in the initiation and progression of cancer." (PMID 28371273, 2017). "Consistently, somatic FEN1 mutations can lead to autoimmunity, chronic inflammation, and cancers." (PMID 39792662, 2025). "The FEN1 endonuclease is involved in BER and DNA replication and has been reported to play important roles in genomic stability, chronic inflammation, autoimmunity and cancers." (PMID 23951112, 2013).
colon cancer (6 papers, 2011 to 2025). "Preclinical studies have demonstrated the efficacy of machine learning in identifying novel compounds (JFD00950) that inhibit FEN1 activity in colon cancer." (PMID 40559911, 2025). "Under unperturbed conditions, CRISPR-Cas9 knocking out FEN1 in the HT29 colon cancer cell line led to an increase in the levels of DPCs in comparison with the isogenic WT cells (1.205 ± 0.115, P = 0.017; fig." (PMID 39792662, 2025). "This study revealed that remimazolam promoted the cell-cycle progression and proliferation of HCT8 colon cancer cells by upregulating CDK1, PTTG1, CDC25C, CDK4, PLK1, PCNA, Ki67, RNASEH2B, FEN1, Cyclin D1,CD44 CDK2, CDKN3, CDC45, IQGAP3, and CDK6." (PMID 38725628, 2024). "More specifically, the APEX1 signaling pathway plays a crucial role in regulating colon CSC growth, whereas FEN1, FANCG and RAD23B were up-regulated in chemo-resistant human colon cancer cell lines." (PMID 35805102, 2022). "In addition inhibition of FEN1, the protein responsible for the removal of the DNA flap following strand displacement during LP-BER, has been shown to block LP-BER and enhance the cytotoxic effect of temozolomide in colon cancer cells." (PMID 21130102, 2011).
lung adenocarcinoma (6 papers, 2010 to 2022). A carcinoma that arises from the lung and is characterized by the presence of malignant glandular epithelial cells. "In lung adenocarcinoma, simultaneous expression of RAD54B and FEN1 proteins was also associated with late-stage LNM in patients." (PMID 35847584, 2022). "Immunohistochemical analysis demonstrated the up-regulation of the protein levels of Mcm2, Fen1, Ube2C and cyclin D1 in lung adenocarcinoma tissue of NNK-exposed Gprc5a-knockout mice compared to the levels in normal lung tissue obtained from the same mice." (PMID 20686609, 2010). "Another study also suggested that FEN1 might contribute to nodal metastasis in lung adenocarcinoma and result in a poor prognosis." (PMID 31534853, 2019). "We further examined the role of FEN1 and RAD54B in the prognosis of lung adenocarcinoma patients by analyzing the clinical outcome with respect to gene expression levels." (PMID 26431531, 2015). "Relationships of FEN1 and RAD54B expression with clinical parameters in lung adenocarcinoma patients." (PMID 26431531, 2015). "Among 24 paired genes, only FEN1 (Flap endonuclease 1) and RAD54B (RAD54 homolog B) were overexpressed in lung adenocarcinoma patients with poor prognosis." (PMID 26431531, 2015). "The interaction between EXOG with APE1, PolG or Lig3, but not between nuclear-specific DNA repair enzymes FEN1 and PolB, was markedly reduced by H2S biosynthesis inhibition in lung adenocarcinoma (but not in normal epithelial cells)." (PMID 27808278, 2016). "Univariate and multivariate analysis of FEN1 and RAD54B in lung adenocarcinoma patients." (PMID 26431531, 2015). "In present study, the overexpression of FEN1 and RAD54B in poorly prognostic lung adenocarcinoma suggests that these two genes might be potential markers for selecting patients at high risk and could be used in the development of effective personalized therapy." (PMID 26431531, 2015).
pancreatic cancer (6 papers, 2018 to 2025). "High expression of FANCA and FEN1 is associated with poor prognosis in pancreatic cancer." (PMID 40847617, 2025). "Thus, flap endonuclease 1 (FEN1) or DNA2 nuclease, which participate in DNA replication and DNA repair, are frequently altered in breast, ovarian, and pancreatic cancers." (PMID 40491064, 2025).
xeroderma pigmentosum (6 papers, 2010 to 2024). Xeroderma pigmentosum (XP) is a rare genodermatosis characterized by extreme sensitivity to ultraviolet (UV)-induced changes in the skin and eyes, and multiple skin cancers. "It exerts biological effects on DNA damage repair and DNA proliferation through binding to the flap endonuclease 1 (FEN-1) and xeroderma pigmentosum (XP) G, and facilitates resynthesis of a new DNA fragment." (PMID 31297133, 2019). "Sequence alignment of T4 RNase H reveals membership to a highly conserved family of nucleases that includes yeast rad27, rad2, human FEN-1, and xeroderma pigmentosa group G (XPG) proteins." (PMID 21129204, 2010). "The excision repair cross complementing group 5 (ERCC5) gene, also known as the xeroderma pigmentosum group G (XPG) gene, is an indispensable component of NER, which belongs to the flap structure-specific endonuclease 1 (FEN1) family." (PMID 22848513, 2012).
prostate carcinoma (5 papers, 2017 to 2023). A carcinoma that arises from epithelial cells of the prostate gland. "Through bioinformatics analyses, we confirmed that FEN1 is upregulated in prostate cancer and is associated with a poor prognosis." (PMID 37326412, 2023). "Few studies have investigated the association between AR and FEN1 in prostate cancer." (PMID 37326412, 2023). "We also evaluated 22Rv1 cells and LNCaP cells to test whether FEN1 expression is linked to cell cycle progression in prostate cancer cells." (PMID 37326412, 2023). "In prostate cancer, FEN1 is overexpressed and is associated with a high Gleason score, which suggests that FEN1 might be a potential marker for prostate cancer diagnosis and therapy." (PMID 28371273, 2017). "In this study, we found that the MEK inhibitor U0126 inhibits FEN1 protein levels in prostate cancer." (PMID 37326412, 2023). "To clarify the expression and role of FEN1 in prostate cancer, we conducted bioinformatics analyses of public databases (TCGA and GSE32892)." (PMID 37326412, 2023). "Further analyses of FEN1 expression and clinical characteristics of prostate cancer demonstrated that higher FEN1 expression was closely related to a higher N stage and Gleason score." (PMID 37326412, 2023). "Low expression of FEN1 in prostate cancer indicated better progression‐free survival (HR = 2.15, p < 0.001)." (PMID 37326412, 2023). "FEN1 expression in prostate cancer tissues was statistically significantly higher than that in normal tissues." (PMID 37326412, 2023). "AR knockdown enhanced DTX‐induced cell apoptosis and cell cycle arrest at the S phase in prostate cancer cells, which was attenuated by FEN1 overexpression." (PMID 37326412, 2023). "FEN1 expression increases with tumour dedifferentiation in prostate cancer, demonstrating that FEN1 expression is closely correlated with Gleason grade." (PMID 37326412, 2023). "To determine the biological function of FEN1 in prostate cancer, we knocked down and overexpressed FEN1 in prostate cancer cells." (PMID 37326412, 2023). "Although we have studied the role of AR and FEN1 in prostate cancer extensively and confirmed the non‐genomic regulatory mechanism of AR on FEN1, there are still several limitations to this work which should be emphasised." (PMID 37326412, 2023). "In particular, FEN1 overexpression reversed apoptosis and cell cycle arrest in prostate cancer cells due to the synergistic effects of AR knockdown and DTX." (PMID 37326412, 2023). "A previous study showed that AR overexpression increased FEN1 protein levels in prostate cancer cells." (PMID 37326412, 2023). "High FEN1 expression levels correlated with lower DTX sensitivity, whereas low FEN1 expression levels correlated with higher sensitivity to DTX in prostate cancer cells." (PMID 37326412, 2023). "We also found FEN1 expression was positively correlated with AR expression in prostate cancer (r = 0.3, p < 0.001)." (PMID 37326412, 2023). "Our research confirms a new mechanism of AR blocking in the treatment of prostate cancer and offers FEN1 as a promising anticancer therapeutic target for prostate cancer treatment in order to overcome DTX resistance." (PMID 37326412, 2023). "We further found that testosterone promoted AR and FEN1 expression in prostate cancer cells, while DTX treatment yielded the opposite results." (PMID 37326412, 2023). "Collectively, our studies demonstrate that AR knockdown improves the DTX sensitivity of prostate cancer cells by downregulating FEN1 through the ERK/ELK1 signalling pathway." (PMID 37326412, 2023). "In prostate cancer cells FEN1 act as a hormone refractory, cells are developed resistance against treatment, some of the small molecular inhibitors (SMI) inhibits the FEN1 activity and cells sensitive to the treatment." (PMID 28187440, 2017). "However, the effect of FEN1 on docetaxel (DTX) sensitivity and the regulatory mechanisms of AR on FEN1 expression in prostate cancer need to be further studied." (PMID 37326412, 2023).